C1R (complement C1r)
Description:
Serine protease component of the complement C1 complex, a multiprotein complex that initiates the classical pathway of the complement system, a cascade of proteins that leads to phagocytosis and breakdown of pathogens and signaling that strengthens the adaptive immune system. C1R catalyzes the first enzymatic step in the classical complement pathway: it is activated by the C1Q subcomplex of the C1 complex, which associates with IgG or IgM immunoglobulins complexed with antigens to form antigen-antibody complexes on the surface of pathogens. Immunoglobulin-binding promotes the autocatalytic cleavage and activation of C1R. Activated C1R then cleaves and activates C1S, the second protease of the classical complement pathway. It is unclear if C1R activates C1S within single, strained C1 complexes or between neighboring C1 complexes on surfaces.
Synonyms: EDS8; EDSPD1
Target class: Serine protease; Enzyme; Serine protease PA clan; Serine protease S1A subfamily; Protease
Gene: Protein-coding gene on chromosome 12 (7,080,213 to 7,092,540, reverse strand). Ensembl gene ENSG00000159403.
Subcellular location: Secreted; Cell surface
Subcellular location (Human Protein Atlas): Cytosol; Nucleoplasm
Pathways (Reactome):
Immune System: Classical antibody-mediated complement activation; Initial triggering of complement; Regulation of Complement cascade
Genetic constraint (gnomAD): Loss-of-function variants: 2 observed, 9.91 expected, observed/expected ratio (o/e) 0.2, 90% interval 0.081 to 0.63. That is too few expected variants to judge how well the gene tolerates losing a copy. Missense variants: 253 observed, 381.65 expected, observed/expected ratio (o/e) 0.66, 90% interval 0.6 to 0.74. Synonymous variants: 127 observed, 150.96 expected, observed/expected ratio (o/e) 0.84, 90% interval 0.73 to 0.98.
Homologues: Orthologues: chimpanzee C1R (99% identical), macaque C1R (92% identical), rat C1r (83% identical), mouse C1ra (81% identical), pig C1R (81% identical), mouse C1rb (80% identical), dog C1R (77% identical), rabbit C1R (77% identical), tropical clawed frog cfi (16% identical), Drosophila melanogaster CG31266 (10% identical), Drosophila melanogaster CG31267 (7% identical). Paralogues in human: C1S (38% identical), C1RL (35% identical), F11 (18% identical), KLKB1 (18% identical), HGFAC (18% identical), F10 (17% identical), F9 (17% identical), HP (16% identical), F7 (16% identical), F12 (16% identical), HPR (15% identical), CFI (15% identical), and 4 more.
Diseases named in the same sentence as C1R in open-access papers:
C1R is named in the same sentence as 106 diseases in open-access papers, as found by Europe PMC text mining. Sharing a sentence is not in itself a finding about the gene and the disease. The quoted sentences say what the papers report.
systemic lupus erythematosus (16 papers, 2015 to 2024). An autoimmune multi-organ disease typically associated with vasculopathy and autoantibody production. "For instance, we know about the existence of cases of systemic lupus erythematosus caused by monogenic mutations in the C1qA, B, C, C1R, DNASE1, DNASE1L3, and ACP5 genes, among many other predisposing genetic variations." (PMID 36900420, 2023). "Paradoxically, patients with homozygous deficiency of the CP components, including C1 (C1q, C1r, or C1s), C4, or C2, have a high risk of lupus or lupus-like disease." (PMID 29892304, 2018). "However, a quantitative analysis of serum C1r has revealed that its deficiency is correlated with the occurrence of autoimmune disorders, such as systemic lupus erythematosus (SLE) and recurrent bacterial infections." (PMID 38002958, 2023). "While deficiency of C1s is associated with early-onset systemic lupus erythematosus and increased susceptibility to bacteria infections, the gain-of- function variants of C1r and C1s may lead to periodontal Ehlers Danlos syndrome." (PMID 36275687, 2022). "Both genes encoding C1s and C1r are located on the short arm of chromosome 12 and several deleterious mutations, resulting in no detectable protein in the serum, have been identified in patients with lupus-like phenotype." (PMID 30459768, 2018). "Therefore, deficiencies of C1q, C1r, C1s, C2, or C4 have been strongly associated with both immunodeficiency as well as autoimmunity, including lupus-like phenotype." (PMID 30459768, 2018). "If this pathway is compromised in systemic lupus erythematosus (SLE) due to deficiency of C1q, or C4, or C1r/s, severe autoimmune reactions occur resulting in tissue injury in the kidneys." (PMID 30135690, 2018). "For example, ficolins and the C1 complex (C1q, C1r, and C1s) detect danger molecules produced by stressed and dying cells, such as surface blebs on apoptotic cells, and deficiencies or dysfunctions in C1 proteins are associated with the autoimmune disease systemic lupus erythematosus (SLE)." (PMID 28149297, 2017). "Lupus-prone families with primary defects of classical complement pathways (C1q, C1r/s, C2, C4A and C4B) revealed the importance of this pathway for lupus pathogenesis." (PMID 30744169, 2019). "Among the strongest, known genetic risk factors for the development of systemic lupus erythematosus (SLE) are deficiencies of the classical complement pathway components (C1q, C1r, C1s, C4, or C2)." (PMID 25688346, 2015). "The DEGs were significantly enriched (Q ≤ 0.05) in the pathway of systemic lupus erythematosus (ID: 05322), which involved 7 DEGs including HIST1H2AL, HIST1H2BJ, HIST4H4, C1 R, C4B_2, C7, and LOC110384692." (PMID 32635817, 2020). "Whilst there was strong colocalisation of DNASE1L3 and C1Q, and to some extent C3 and C1R, there was no colocalisation between DNASE1L3 and the other lupus related genes, including genes associated with apoptosis." (PMID 38744839, 2024). "Likewise, RT1-Db1, C1r, RT1-Da are the key genes that link three metabolic-related pathways, including phagosome, systemic lupus erythematosus, and Staphylococcus aureus infection." (PMID 37090774, 2023).
COVID-19 (8 papers, 2021 to 2024). A disease caused by infection with severe acute respiratory syndrome coronavirus 2. "The gene C1S, associates with two other complement components C1r and C1q in order to yield the C1 complex, which then triggers the subsequent steps of the classical pathway of complement activation, and is found to be upregulated in the lungs of severe COVID-19 patients in our IPA analysis." (PMID 34899680, 2021). "Neutrophils from patients with severe COVID-19 were characterized by increased detection of classical complement pathway components, such as C1R and C1S." (PMID 34403366, 2021). "A number of studies have shown that the sign of COVID-19 was the cytokine storm with elevated levels of interleukin-6 (IL-6), IL-1β, complement C1r (C1R), tumor necrosis factor-alpha (TNF-α), chemokine (C-C-motif) ligand 2 (CCL2), and granulocyte-macrophage colony-stimulating factor (GM-CSF)." (PMID 35726234, 2022). "Self-made C1 complex (C1q, C1s, C1r) can translocate to the monocyte cell surface and activate the complement cascade, thus suggesting a possible role for monocyte-driven classical complement activation during COVID-19." (PMID 35250994, 2022). "Survival analyses revealed a significant correlation between high expression of C1R, CCL2, and TNFRSF1A in the coronavirus disease-COVID-19 pathway and the poor survival in GBM patients." (PMID 35726234, 2022). "The high expression levels of C1R, CCL2, and TNFRSF1A in coronavirus disease-COVID-19 pathway were significantly related to the low survival in GBM patients." (PMID 35726234, 2022). "Clusters A to C contain proteins with lower levels in COVID-19 convalescents, e.g. proteins functioning in cell adhesion and platelet degranulation (e.g. fibrinogen A (FGA), VWF), and innate immunity/the complement system (e.g. C1R, C1S, C1QA, C1QC, and GGH)." (PMID 38396092, 2024). "We believe that the C1R, CCL2, and TNFRSF1A genes in the coronavirus-COVID-19 pathway may be activated in GBM patients, making GBM patients more susceptible to novel coronavirus infection." (PMID 35726234, 2022). "This study also found increased C1r and C1s, the proteases inhibited by C1-INH, in COVID-19." (PMID 34458849, 2021). "We found that the high expression of C1R, CCL2, and TNFRSF1A genes was particularly associated with the low survival in GBM patients, while other 41 DEGs enriched in the pathway of coronavirus disease-COVID-19 were not significantly connected with the overall survival of GBM patients." (PMID 35726234, 2022).
Periodontal EDS (7 papers, 2016 to 2022). "Periodontal EDS—Recently, heterozygous pathogenic gain-of-function variants in the C1R and C1S genes, encoding the C1r and C1s subunits of the first component of the classical complement pathways, were associated with periodontal EDS (pEDS)." (PMID 35205310, 2022). "In conclusion, leukoencephalopathy appears to be part of the clinical spectrum in periodontal EDS with C1R mutations, as it was evident in all adult individuals studied by MRI known to us." (PMID 30535813, 2019). "Here, we report that leukoencephalopathy appears to be a general feature of periodontal EDS caused by C1R mutations." (PMID 30535813, 2019). "Periodontal EDS is a distinct clinical entity that we have now shown to be caused by mono-allelic missense or in-frame insertion/deletion alterations in C1R or C1S, the genes that encode complement 1 subunits C1r and C1s." (PMID 27745832, 2016). "The pathogenesis of the leukoencephalopathy caused by C1R mutations in periodontal EDS is unclear." (PMID 30535813, 2019). "We previously identified heterozygous missense mutations in the C1R and C1S genes, coding for the complement C1 proteases, in patients affected by periodontal EDS, a specific EDS subtype hallmarked by early severe periodontitis leading to premature loss of teeth and connective tissue alterations." (PMID 31921203, 2019). "Periodontal Ehlers-Danlos syndrome (pEDS) is a rare subtype of EDS with autosomal-dominant inheritance caused by mutations in two linked genes, C1R and C1S, which encode complement 1 subunits C1r and C1s." (PMID 36237549, 2022). "Additionally, the C1q subunit—binding partner of the C1s-C1r tetramer—has a triple helical structure, which resembles collagen; some features of periodontal EDS may be due to abnormal C1r/C1s interaction with extracellular matrix components." (PMID 30535813, 2019).
Ehlers-Danlos syndrome (6 papers, 2017 to 2022). The Ehlers–Danlos syndromes (EDS) are a clinically and genetically heterogeneous group of heritable connective tissue disorders (HCTDs) characterized by joint hypermobility, skin hyperextensibility, and tissue fragility. "Cell type-specific expression patterns confirmed fibroblast as particularly high expressors of the C1S and C1R gene, mutated in Ehlers-Danlos syndrome, periodontal type." (PMID 34566966, 2021). "In monogenic Ehler Danlos Syndrome the alterations in C1R or C1S genes encoding for complement 1 subunits C1r and C1s has been documented as a link between connective tissue pathology with classical complement pathway." (PMID 29760828, 2018). "Our interest in this disease context opened through a collaboration with scientists from Innsbruck Medical University, who discovered heterozygous mutations in C1 subunit genes C1R and C1S, which were clearly associated with a specific periodontal subtype of Ehlers-Danlos Syndromes (EDS)." (PMID 35572583, 2022).
cutaneous squamous cell carcinoma (5 papers, 2022 to 2026). "The growth of cutaneous squamous cell carcinoma and non-small-cell lung cancer was promoted by tumor-cell-derived complement components C1r and C1s." (PMID 35726234, 2022). "It is reported that the knockdown of C1r promotes apoptosis of cutaneous squamous cell carcinoma cells." (PMID 34813686, 2022). "Regarding C1R, there is no information related to CC; however, what has been published to date relates this gene to tumor growth, vascularization, and invasion in cutaneous squamous cell carcinoma." (PMID 36672296, 2023).
lung cancer (5 papers, 2020 to 2025). A malignant neoplasm involving the lung. "As matter of secretome profiling and IPA prediction, the Fibronectin, C1r, and C1s are potential of nephrotoxicity linked to paraneoplastic effects on glomerular pathogenesis in these lung cancer mice." (PMID 33260558, 2020). "In vitro, lung cancer cells produced C5a independently of the expression of factor B, properdin, C1q, C1r, C1s, C1, and C4." (PMID 40370471, 2025). "Significant amplification or mutation events are observed in pancreatic, colorectal, and lung cancers, with minimal alterations in hematologic malignancies such as AML, indicating a potential role for C1r in solid tumor progression." (PMID 39254172, 2024). "High expression of C1R/C3 is associated with high pathological grade and poor prognosis in PAAD, COAD, and lung cancer patients." (PMID 39254172, 2024). "A previous study had shown the serum concentration of C1R had prognostic value in non‐small cell lung cancer." (PMID 34813686, 2022). "High levels of C1R were reported in nonsmall cell lung cancer compared to control groups." (PMID 36672296, 2023).
Autoimmunity (3 papers, 2009 to 2023). The occurrence of an immune reaction against the organism's own cells or tissues. "Whether this function requires the C1r and C1s subunits is unclear, but deficiencies in a subunit of C1q can increase susceptibility to autoimmunity." (PMID 19379516, 2009). "In this context, the four earliest components of the complement classical pathway, i.e., C1q, C1r, C1s, and C4, may be considered as an essential albeit insufficient tolerance mechanism against dead cell-induced autoimmunity." (PMID 37359557, 2023).
complement deficiencies (3 papers, 2016 to 2023). "Monogenic SLE was first described in the 1970s and found to be caused by early complement deficiencies (C1q, C1r/C1s, C2, and C4)." (PMID 37622085, 2023). "Heterozygous GOF mutations in C3 are now added to the list of genetic complement deficiencies causing vasculitis such as C1q, C1r, and C1s deficiency, complement factor I deficiency and complement C2 and C4 deficiency." (PMID 30443255, 2018). "Deficiencies in subcomponents C1r and C1s were among the earliest reports linking complement deficiency with human glomerulonephritis or a lupus-like disease." (PMID 26913032, 2016). "In the following sections, we will describe genetic complement deficiency states associated with SLE for each component of the early CP (C1q, C1r, C1s, C4, and C2)." (PMID 26913032, 2016).
glaucoma (3 papers, 2017 to 2024). Increased pressure in the eyeball due to obstruction of the outflow of aqueous humor. "We quantified the majority of key proteins associated with classical complement pathway, such as C1q, C1s, C1r, C4a, C4b, C3, C5, C6, C7, C8a, C8b, C8g and C9, as up-regulated in glaucoma condition for both vitreous and retinal tissues when compared to the controls." (PMID 28978942, 2017). "Earlier studies have shown that immune-related proteins and several members of the complement components including C1S, C1r, C7-C9, and CFH are activated in glaucoma." (PMID 33808966, 2021).
glioblastoma (3 papers, 2022 to 2026). The most malignant astrocytic tumor (WHO grade IV). "Tumor electric field therapy (TEFT) inhibits glioblastoma progression by suppressing the TGF‐β/SMAD2/3/STAT3/C1R axis to reverse epithelial‐mesenchymal transition (EMT)." (PMID 41489302, 2026). "This study identifies C1R as a key molecular target of TEFT and a potential biomarker for the aggressive mesenchymal subtype of glioblastoma." (PMID 41489302, 2026). "To detect the expression levels of C1R, CCL2, and TNFRSF1A in glioblastoma, we analyzed the mRNA levels of GBM patients and glioblastoma cells." (PMID 35726234, 2022). "The results indicated that the expression of C1R, CCL2, and TNFRSF1A might promote the development of glioblastoma and might be used as molecular biomarkers of prognosis and immune infiltration in GBM patients in the future." (PMID 35726234, 2022). "The results suggested that the expression of C1R, CCL2, and TNFRSF1A might promote the development of glioblastoma." (PMID 35726234, 2022). "Moreover, the mRNA expression levels of C1R, CCL2, and TNFRSF1A in glioblastoma cells or in GBM patients were found to be strongly upregulated, and the mRNA expression levels of these three genes were positively associated with each other." (PMID 35726234, 2022).
glioma (3 papers, 2020 to 2026). A benign or malignant brain and spinal cord tumor that arises from glial cells (astrocytes, oligodendrocytes, ependymal cells). "Analyses of CGGA, Gravendeel, Rembrandt, and TCGA datasets consistently showed that C1R expression levels increased with glioma grade progression, with the highest expression in GBM." (PMID 41489302, 2026). "At the glioma tissue level, we examined C1R expression patterns across multiple cohorts." (PMID 41489302, 2026). "Additionally, this model and four of its genes (CLECL5A, SERPING1, CHI3L1 and C1R) were found to be associated with immune cell infiltration, and further study demonstrated that these four genes might drive the hypoxic phenotype of perinecrotic GBM, which affects hypoxia‐induced glioma stemness." (PMID 33009892, 2020).
hereditary angioedema (3 papers, 2020 to 2026). Hereditary angioedema (HAE) is a genetic disease characterized by the occurrence of transitory and recurrent subcutaneous and/or submucosal edemas resulting in swelling and/or abdominal pain. "Inhibitors of C1r/s obtained as recombinant proteins or from human plasma, as used in our in vivo studies, are available in the clinic with a primary indication for the treatment of hereditary angioedema." (PMID 37927228, 2023).
ischemic stroke (3 papers, 2021 to 2025). A stroke disorder caused by obstruction of blood flow to the brain, due to thrombotic (local blood clot formation) or embolic (due to a blood clot or other material traveling from another site) event. "We found that fat mass independently increased plasma levels of all protein mediators (COL6A3-derived endotrophin, F11, PCSK9, C1R and SPATA20) and increased the odds of type 2 diabetes, CAD and ischemic stroke." (PMID 39856218, 2025). "A2MG, C1QB, C1R, and HRG were found to be potential predictors of ischemic stroke development; however, further validation and investigation are necessary to determine the roles of all of these differentially expressed proteins in ischemic stroke development." (PMID 34912031, 2021). "We revealed marked upregulation of four proteins (A2MG, C1QB, C1R, and HRG) in EVs enriched fractions by 7.3 ± 4.4 years before ischemic stroke onset, indicating their potential as biomarkers for predicting future ischemic stroke events." (PMID 34912031, 2021). "In comparison to age- and sex-matched controls who did not develop any brain lesion, alpha-2-macroglobulin (A2MG), complement C1q subcomponent subunit B (C1QB), complement C1r subcomponent (C1R), and histidine-rich glycoprotein (HRG) were significantly upregulated in the ischemic stroke patients." (PMID 36140248, 2022). "Alpha-2-macroglobulin (A2MG), complement C1q subcomponent subunit B (C1QB), complement C1r subcomponent (C1R), and histidine-rich glycoprotein (HRG) were significantly upregulated by 2.21-, 2.15-, 2.24-, and 2.16-fold, respectively, in the ischemic stroke group as compared to the control group." (PMID 34912031, 2021). "Considering that C1R and C1QB are part of the C1 complex that initiates the classical pathway of the complement cascade, our results indicate that an abnormal complement status might be involved in the development of ischemic stroke." (PMID 34912031, 2021).
periodontitis (3 papers, 2016 to 2019). An acute or chronic inflammatory process that affects the tissues that surround and support the teeth. "No mutations in C1R or C1S were detected in 71 individuals with aggressive periodontitis, which is a main differential diagnosis to pEDS." (PMID 27745832, 2016).